CDC25A (cell division cycle 25A)
Diseases named in the same sentence as CDC25A in open-access papers (continued):
Sharing a sentence is not in itself a finding about the gene and the disease.
cancer (continued). "Unlike cdc25B, the incidence of cdc25A overexpression did not decrease in carcinomas with aggressive phenotypes." (PMID 12085185, 2002). "It is known that Pim kinases act on the proliferation of cancer cells by interfering with the cell cycle checkpoints, by phosphorylating cell division cycle 25 (CDC25) family members that are important regulators of the G1/S (CDC25A,) and G2/M (CDC25C,) checkpoints." (PMID 40165380, 2025). "Since HIF-1α is involved in hypoxia-induced senescence by activating cyclin-dependent kinase inhibitors p21CIP1 and p27KIP1 or inhibiting M-phase inducer CDC25A, anti-HIF-1α strategies may increase the action of anti-cancer agents by abating the senescent phenotype." (PMID 36846589, 2023). "However, the role of USP29 in regulating Cdc25A protein stability and its function during cancer progression have not been studied." (PMID 34071237, 2021). "Finally, the experiments using cancer cell lines and organoids confirmed that CDK1, CCNB, and CDC25A could induce LUAD proliferation and colony formation." (PMID 34446056, 2021). "However, CDC25C was only upregulated in T2-KD OVCAR4 and JOSH2 cancer cells compared to their corresponding control cells and there was no change in the expression of CDC25A in any of the T2-KD cells compared to its respective controls." (PMID 33023532, 2020). "To ask whether FLT3-ITD cells are dependent of CDC25A activity for their proliferation, we first used IRC-083864, a potent pharmacological inhibitor of CDC25 (A, B and C) previously characterized in vitro and in vivo in different cancer models." (PMID 26515730, 2015). "Thus, CDC25-inhibitors targeting either CDC25A or Cdc25B may have the useful property of exhibiting anti-tumor activity in those cancers overproducing these phosphatases without inducing the deleterious GI side effects associated with radiation and chemotherapy." (PMID 21283624, 2011). "When compared with non-cancerous cells, CDC25A and CDC25B were strongly expressed in the cytoplasm of cancer cells, with positive (+) classification in 46% (46 cases) and 48% (48 cases), respectively." (PMID 11487274, 2001). "CDC25A and CDC25B, being oncogenes, are over-expressed in many different primary human cancers, such as head and neck cancer, poorly differentiated non-small cell lung cancer, advanced stage gastric cancer, non-Hodgkin's lymphomas, colon cancer, esophagus cancer, breast cancer, and ovarian cancer." (PMID 18269767, 2008). "However, CDC25A knockdown did not inhibit LUAD cell line proliferation but could effectively suppress LUAD organoid growth, indicating that an organoid could be used as an effective tool to study cancer biology in LUAD." (PMID 34446056, 2021).
tumor (127 papers, 2001 to 2025). "Subsequent scrutiny of tumor stemness risk genes (TSRGs) culminated in the identification of CDC25A for detailed investigation." (PMID 38613794, 2024). "The inactivation of GSK3β, the kinase for CDC25A priming, has been associated with CDC25A overproduction in human tumor tissues." (PMID 37686524, 2023). "A recent study has shown that USP17 can interact with Cdc25A and remove the K48-linked polyubiquitin chains, which target Cdc25A for proteasomal degradation, in order to subvert cell cycle and promote tumor progression." (PMID 26610488, 2015). "The significant association of reduced CDC25A expression with overexpression of p-EGFR in this tumor suggests their synergistic action in development of tumor." (PMID 23675485, 2013). "Moreover, CDC25A expression was significantly associated with tumour invasion and poor tumour differentiation." (PMID 33282948, 2020). "In addition, overexpression of Cdc25A and Cdc25B is often associated with high-grade tumours and poor prognosis." (PMID 27485204, 2016). "Similarly, the higher pathological component risk rating, the more proportion of YBX1 and CDC25a expression in tumor lesions." (PMID 27384875, 2016). "Suppression of cdc25A is implicated in the inhibition of tumour growth-promoting MAPK activity." (PMID 20551952, 2010). "Bioinformatics analysis has shown that several proteins interacting with MES are strongly associated with tumor progression, including PAK1, TNF, SRC, and CDC25A." (PMID 40699726, 2025). "CDC25A represents a potential protein that promotes tumor progression through cell cycle regulation." (PMID 40216745, 2025). "Growing evidence suggests that CDC25A expression is increased in various tumor tissues and plays an important role in promoting tumor initiation and progression." (PMID 39974663, 2025). "In agreement with the in vitro findings, the expression of NRAS, p-ERK1/2, CDK4, Cdc25A, and CydlinD1 was inhibited in tumor grafts with the treatment of DHA." (PMID 38778121, 2024). "miR-99a-5p plays an anti-tumor role in tumor metastasis by targeting CDC25A/IL6 to hinder the Epithelial–Mesenchymal Transition (EMT) process in human cervical squamous cell carcinoma." (PMID 37925811, 2024). "The scatter plot unveiled a notably stronger correlation between CDC25A and the tumor stemness index compared to ASCL2." (PMID 38613794, 2024). "When the prodrug is taken up by the tumor cells, it can bind CDC25A in the entity and be engaged in the normal transportation process of the cell." (PMID 38948069, 2024). "BPTF promotes CRC cell cycle progression, thus CRC proliferation and overall tumour progression by targeting Cell division cycle 25 A (Cdc25A)." (PMID 38067326, 2023). "In such cases, the stable expression of β-TrCP1, potentially through the downregulation of CDC25A, leads to the negative regulation of cell motility, cell growth in soft agar, and tumor growth in xenografts." (PMID 37686524, 2023). "It has a well-established role in the DDR pathway, potentially playing a role in nonhomologous end joining and cell cycle regulation via influences on stability of Cdc25a, potentially giving tumour cells a growth advantage." (PMID 35409400, 2022). "The investigation of the common 68 proteins in The Human Protein Atlas database (; proteinatlas.org) revealed a similar association between tumor and normal tissues at the protein level for CKAP2L, AURKB, CDC25A, APIP, and LGALS3." (PMID 36529823, 2022). "The reduction of these genes in the R-PTP-κ-high group indicates that R-PTP-κ negatively regulates the expression of E2F1 target genes CCNE1 and CDC25A in various tumor tissues." (PMID 36551956, 2022).
tumor (continued). "As one of the cell cycle regulators, CDC25A participates in the radioresistance of various tumor cells)." (PMID 35309118, 2022). "When endogenous CDC25A was depleted, foreign CDC25A (△E6) significantly enhanced tumor growth, while CDC25A(L) overexpression had a limited effect." (PMID 36539837, 2022). "Previous studies, including our own recent work, identified DUBs (Dub3, USP3, and HAUSP) involved in Cdc25A-dependent cell cycle and tumor progression." (PMID 34071237, 2021). "In this study, a systemic analysis was performed to reveal CDK1, CCNB2, and CDC25A as the hub genes; the expression of these genes increased in tumor tissues and predicted poor prognosis in LUAD." (PMID 34446056, 2021). "On the other hand, transplantation of USP29-depleted cells reconstituted with Cdc25A led to an increased tumor volume." (PMID 34071237, 2021). "Taken together, our study results suggested that USP29 facilitated tumor metastasis and progression and exerted its effect by stabilizing and deubiquitinating Cdc25A." (PMID 34071237, 2021). "The staining intensity of Ki-67, an important marker for tumor proliferation, was significantly reduced when CDC25A was downregulated." (PMID 34266408, 2021). "A nude mouse xenograft model was used to examine the effects of the Cdc25A/ErbB2 axis on tumour growth in vivo." (PMID 34743185, 2021). "The expressions of SNHG11, miR-184, and CDC25A mRNA in the tumor specimens (n = 6) of mice were detected." (PMID 33816469, 2021). "Linear regression analyses were performed to evaluate the relation between expression of replication stress markers versus clinicopathological characteristics and tumor expression of Cdc25A, Cyclin E, and c-Myc." (PMID 32964114, 2020). "To further investigate this question, we analyzed the tumor same sample set by using Gene Set Enrichment Analysis (GSEA) in order to identify curated gene signatures whose expression changed significantly in CDC25A high STS patient samples." (PMID 32911761, 2020). "The ssGSEA performed on the entire sample revealed an up-down regulation of those pathways enriched in CDC25A high tumor subgroup." (PMID 32911761, 2020). "Clinical analysis has indicated that the aberrant activation of the B7-H3/CDC25A axis is significantly related to tumor stage." (PMID 32127943, 2020). "Samples nicely separate in two clusters (tumor and normal tissue) accompanied by a concordance with CDC25A expression levels." (PMID 32911761, 2020). "More and more studies have shown that the expression of CDC25A is regulated by multiple miRNAs, and it participates in the radiation resistance of various tumor cells." (PMID 31505105, 2019). "With regards to their functions, CHEK1, RAD51 and CDC25A have been suggested to promote tumor development, while GADD45A can act as a tumor suppressor." (PMID 30042885, 2018). "β-TRCP has previously been shown to function as a tumor suppressor by targeting various oncoproteins such as β-catenin, CDC25A, FBXO5, IκB and DEP domain-containing mTOR-interacting protein (DEPTOR)." (PMID 29497989, 2018). "Our data indicates that compared to normal epithelium, low basal/ parabasal expression of RBSP3 was maintained, while the high expression of LIMD1 and CDC25A were lost during tumour development due to genetic/ epigenetic alterations." (PMID 29672635, 2018). "This is strongly supported by our results that CPX did not significantly reduce the mRNA level of Cdc25A or the protein synthesis rate of Cdc25A, but remarkably promoted the protein degradation rate of Cdc25A in tumor cells." (PMID 28680535, 2017). "Other published targets, linked to an involvement in the regulation of apoptosis and tumour invasion, include BCL2, CDC25A and TNFAIP2." (PMID 28736583, 2017). "Here we show that CPX inhibits cell proliferation in part by downregulating the protein level of Cdc25A in tumor cells." (PMID 28680535, 2017).
tumor (continued). "Taken together, the findings from this group and others support the notion that CPX inhibits tumor cell proliferation by multiple mechanisms, and Cdc25A is one of the critical targets of CPX." (PMID 28680535, 2017). "CDC25A is one of the most crucial cell cycle regulators in controlling G1/S and G2/M entry that enhance mitosis and tumor growth." (PMID 28120940, 2017). "Our findings demonstrate that NPAS2 has a critical role in HCC cell survival and tumor growth, which is mainly mediated by transcriptional upregulation of CDC25A." (PMID 28333141, 2017). "The IHC results also confirmed the activation of CHK1/CDC25A/CDK2 pathway in xenograft tumor generated from Mus81‐inhibited HepG2 cells under EPI treatment." (PMID 26714930, 2016). "A statistically significant correlation was observed between SH3GL2 and CDC25A alterations (p = 0.05) in tumor samples." (PMID 23675485, 2013). "Overexpression of Cdc25A, which frequently occurs in multiple tumor types, leads to accelerated entry of cells into S-phase and mitosis." (PMID 21310058, 2011). "Western blotting analysis of tumor lysates showed that H69 tumors isolated from capsaicin treated mice had lower levels of cyclin E, TS, cdc25A and cdc6, as compared to control untreated mice." (PMID 20421925, 2010). "Tumour suppression occurred via direct targeting of cell division cycle 25 A (CDC25A) and c-MYC." (PMID 41379397, 2025). "Additionally, CDC25A plays significant roles in apoptosis, cell metabolism, and tumor cell metastasis." (PMID 41373559, 2025). "This indicates that YBX1 regulates tumor growth through the CDC25a pathway." (PMID 40799245, 2025). "From a clinical perspective, targeting CDC25A-regulated cholesterol may represent a promising therapeutic approach for addressing circulatory tumor cell dissemination." (PMID 39390252, 2024). "Knockdown of USP47 induces CDC25A accumulation and the inhibition of tumor growth." (PMID 37686524, 2023). "As such, we infer that CDC25A can promote the progression and drug resistance of CC by accelerating cell cycle progression, cell migration, colony formation, and enhancing the resistance of tumor cells to DNA-damaging agents." (PMID 36880057, 2023). "CDC25 phosphatases (CDC25A/B/C) play essential roles during normal cell division as regulators of CDK activity, and their increased activity is associated with cell proliferation and tumor progression." (PMID 36601903, 2023). "The downregulation of Nek11 could therefore be beneficial for tumour growth, as this would escalate Cdc25a concentrations within the cell and result in uncontrolled cell division." (PMID 35409400, 2022). "Altogether, our analysis suggests that the consistent downregulation of TTLL11 across tumors may be explained by the overexpression of CCNE1 or CDC25A as part of a tumor-specific transcriptional program." (PMID 36414642, 2022). "Moreover, NSG nude mice transplanted with USP29-depleted cells significantly reduced the size of the tumors, whereas the reconstitution of Cdc25A in USP29-depleted cells significantly increased the tumor size." (PMID 34071237, 2021). "Finally, we demonstrated that USP29 was critical in promoting Cdc25A-dependent cell cycle progression and tumor formation in vivo." (PMID 34071237, 2021). "Moreover, the role of B7-H3/CDC25A axis in regulating chemoresistance in vivo in the xenograft tumor models by intraperitoneal injection of oxaliplatin (L-OHP) and CDC25A inhibitors." (PMID 32127943, 2020). "Indeed, we also observed correlations between mRNA expression of CCNE1 or CDC25A and copy number load in various tumor types." (PMID 33028815, 2020). "In this study, we assessed whether oncogene-induced replication stress as a result of Cyclin E1 or Cdc25A overexpression affects mitotic behavior of tumor cells and genome instability." (PMID 33028815, 2020).
tumor (continued). "Interestingly, although CDC25A overexpression alone is insufficient to drive tumor initiation, CDC25A has a clear role as rate-limiting oncogene in transformation by RAS10." (PMID 30718768, 2019). "Functional studies have reported that miR-483-3p may act as an oncogene by targeting BBC3/PUMA directly or tumor suppressor via repression of multiple targets including CDC25A, BIRC5, and RAN." (PMID 29717264, 2018). "However, CPX, at low concentrations (≤5 μM), drastically reduces the cellular protein level of Cdc25A, which results in increased inhibitory phosphorylation of G1-CDKs, leading to the accumulation of cells in G1 phase of the cell cycle in tumor cells." (PMID 29725502, 2018). "YBX1 regulates tumor growth via CDC25a pathway in human lung cancer." (PMID 30250023, 2018). "Similarly, CDC25A phosphatase is involved in cellular processes such as response to DNA damage, mitotic entry and is also important for tumour growth." (PMID 29672635, 2018). "Moreover, BMAL1, another core clock transcription factor, was identified to heterodimerize with NPAS2 to bind to the E-box element in the promoter of CDC25A and be associated with the NPAS2-mediated tumor cell survival in HCC." (PMID 28333141, 2017). "Many types of human tumour cells overexpress the dual-specificity phosphatase Cdc25A." (PMID 27485204, 2016). "Furthermore, we also showed that inhibition of YBX1 suppressed the expression of CDC25a in tumor tissues by IHC analysis as well as Ki 67 and stimulated cleaved caspase 3 expression." (PMID 27384875, 2016). "So we hypothesized that if YBX1 could bind to CDC25a promoter and up-regulate CDC25a expression to promote tumor cell overcoming cell cycle checkpoint restriction to satisfy unlimited malignant amplification." (PMID 27384875, 2016). "Moreover, inhibition of YBX1 by siRNA suppressed tumorigenesis in a xenograft mouse model and down-regulated the expression of YBX1, CDC25a, Ki67 and cleaved caspase 3 in the tumor tissues of mice." (PMID 27384875, 2016). "Interfering with CDC25a suppresses the growth and invasion in tumor cells." (PMID 27884160, 2016). "Patients whose tumours had low (0–4 staining) Cdc25A Y59 phosphorylation (24 cases) had a median survival of 168 weeks; those whose tumours had high (4.1–8 staining) levels of Cdc25A Y59 phosphorylation (64 cases) had significantly lower median survival duration of 60 weeks." (PMID 27485204, 2016). "Disruption of Cdc25A function during tumor formation due to altered Cdc25A acetylation might impair the ability of cells to control cell cycle checkpoints and thereby increase genomic instability." (PMID 26967250, 2016). "Our data suggests that overexpression of EGFR protein might be due to the impairment of the SH3GL2 associated endocytosis mechanism, whereas down regulation of CDC25A in this tumor might lead to the EGFR protein in its active state." (PMID 23675485, 2013). "Tumor cells, however, could experience an effect mostly on Cdc25A, which is degraded after Chk1 activation." (PMID 23755068, 2013). "The expectation was that mice expressing Cdc25A S88F would have increased amounts of the protein due to a reduction in its degradation and that cells would undergo unscheduled replication, display genomic instability and early tumor onset in the progeny." (PMID 21310058, 2011). "CDC25A overexpression in primary human epithelial cells was also previously shown to promote genomic instability at common fragile sites, thus accounting for the oncogenic consequences of its increased expression in human tumours." (PMID 20128929, 2010). "Furthermore, it has been reported that IL-6 was able to induce degradation of Cdc25A by STAT3 activation, which would form a repressor complex with the Rb tumour suppressor to occupy the Cdc25A promoter and block its induction." (PMID 17987036, 2007). "Additionally, both B7-H3 and CDC25A expression increased with tumor stage." (PMID 32127943, 2020).